MAD2L2 (mitotic arrest deficient 2 like 2)
Diseases named in the same sentence as MAD2L2 in open-access papers (continued):
Sharing a sentence is not in itself a finding about the gene and the disease.
lung carcinoma (7 papers, 2020 to 2024). "Compared with other SNPs, MAD2L2 rs746218 was significantly associated with PFS in the recessive model analysis in patients with lung cancer who received platinum-based chemotherapy." (PMID 35899106, 2022). "Both molecules sensitize lung cancer cell lines to cisplatin, disrupt the formation of the MAD2L2-Rev1 complex and increase DNA damage, hence underlining their potential as lead compounds for developing novel TLS inhibitors for improving chemotherapy treatments." (PMID 35163901, 2022). "Multivariate Cox regression adjusted for age, gender, histology type, smoking status, stage, and metastasis showed that the MAD2L2 rs746218 polymorphism was significantly related to PFS in patients with lung cancer in the recessive model (p = 0.039, OR = 5.31, and 95% CI = 1.09–25.93)." (PMID 35899106, 2022). "Our results showed that MAD2L2 rs746218 and TNFRSF1A rs4149570 were significantly associated with prognosis in patients with lung cancer who received platinum-based chemotherapy." (PMID 35899106, 2022). "In summary, our study showed that MAD2L2 rs746218 was significantly associated with platinum-based chemotherapy, and PFS and TNFRSF1A rs4149570 was significantly associated with OS time in patients with lung cancer treated with platinum-based chemotherapy." (PMID 35899106, 2022). "Association of the MAD2L2 rs746218 polymorphisms and PFS in lung cancer patients." (PMID 35899106, 2022). "Polymorphisms of MAD2L2 rs746218 and TNFRSF1A rs4149570 polymorphisms may be biomarkers for predicting prognosis in patients with lung cancer treated with platinum-based chemotherapy." (PMID 35899106, 2022). "In this study, we also investigated the correlations between 35 polymorphisms in 9 DNA repair genes (XRCC3, BRCA2/ZAR1L, XPC, RAD52, MAD2L2, NFKB1, NFKBIA, TNFRSF1A, and FASN) with platinum-based chemotherapy prognosis in 399 patients with lung cancer." (PMID 35899106, 2022). "In EFV treated A549 lung cancer cells, EFV significantly decreased expression levels of both MAD2L2 (fold changes, **p < 0.01 and ***p < 0.001) and AURKB (fold changes, p < 0.001) genes at 24 h and 48 h." (PMID 33110481, 2020). "Our results showed that MAD2L2 rs746218 and TNFRSF1A rs4149570 may be biomarkers for predicting the prognosis of patients with lung cancer in response to platinum-based chemotherapy." (PMID 35899106, 2022).
melanoma (5 papers, 2020 to 2024). A malignant, usually aggressive tumor composed of atypical, neoplastic melanocytes. "The expression of MAD2L2 is significantly elevated in melanoma compared to adjacent tissues, and patients with higher expression levels have a worse prognosis." (PMID 38017538, 2023).
bladder cancer (2 papers, 2024). "MAD2L2 expression was higher in bladder cancer tissues compared to normal tissues in unpaired and paired samples, and high MAD2L2 expression was associated with poor prognosis for BC patients in the TCGA database." (PMID 38515112, 2024). "AURKB interacts with and regulates MAD2L2 expression in bladder cancer cells." (PMID 39456780, 2024).
brain cancer (2 papers, 2022 to 2024). A primary or metastatic malignant neoplasm affecting the brain. "Additionally, TTI2 in prostate, APC in breast, MAD2L2 in pan-cancer, HERC2 in prostate, and MDN1 in brain cancer associated with the mutation component dMMRICA." (PMID 35764656, 2022).
hepatic cancer (2 papers, 2015 to 2023). "The results revealed higher expression levels of STAM, ANXA5, and MAD2L2 in liver cancer cell lines compared to normal hepatocytes." (PMID 38049741, 2023). "The present study demonstrated that the expression levels of ANXA5, MAD2L2, and STAM in liver cancer cell lines were significantly higher than those in normal hepatocytes." (PMID 38049741, 2023). "In addition, in liver cancer cell lines MHCC97H, MHCC97L, and HCCLM3, which exhibited relatively high expression levels, we knocked down STAM, ANXA5, and MAD2L2 using siRNA and observed alterations in the biological functions of HCC cells." (PMID 38049741, 2023).
hepatocellular carcinoma (2 papers, 2023). A malignant tumor that arises from hepatocytes. "We constructed the prognostic risk score for patients with hepatocellular carcinoma as follows: risk score = (0.3519) × PPM1G + (0.0637) × FKBP1A + (0.0673) × STAM + (0.0373) × MAD2L2 + (0.0031) × TBL1XR1 + (0.0172) × ANXA5." (PMID 38049741, 2023).
ovarian clear cell cancer (2 papers, 2017 to 2024). An invasive malignant neoplasm that arises from the ovary and is characterized by a predominance of clear and hobnail malignant epithelial cells. "Recent research suggests that reduced MAD2L2 expression may increase cisplatin sensitivity in ovarian clear-cell carcinoma cells." (PMID 38167649, 2024).
pancreatic cancer (2 papers, 2022 to 2023). "In pancreatic cancer, similar to REV7/MAD2L2, low expression of ZRANB3 and HLTF shows poorer survival probabilities than those with high expression." (PMID 35955544, 2022).
renal cell carcinoma (2 papers, 2009 to 2010). "Previously, we identified the mitotic arrest deficient protein MAD2B (MAD2L2) as a bona fide interactor of the renal cell carcinoma (RCC)-associated protein PRCC." (PMID 19753112, 2009).
sarcoma (2 papers, 2022 to 2025). A usually aggressive malignant neoplasm of the soft tissue or bone. "Both XRCC2 and MAD2L2 higher expression was associated with worse survival in the TCGA sarcoma cohort." (PMID 36110934, 2022).
glioblastoma (1 paper, 2023). The most malignant astrocytic tumor (WHO grade IV). "Next, we investigated the mechanisms underlying the dysregulation of MAD2L2 expression in glioblastoma." (PMID 38017538, 2023). "The impact of MAD2L2 on glioblastoma cell behaviors was assessed through cell viability assays (CCK8), colony formation assays, 5-Ethynyl-2ʹ-deoxyuridine (EDU) incorporation assays, scratch assays, and transwell migration/invasion assays." (PMID 38017538, 2023). "Further investigation revealed that MYC proto-oncogene (c-MYC) mediated the functional role of MAD2L2 in glioblastoma, which was further validated through a rescue experiment." (PMID 38017538, 2023). "Our study elucidated the role of MAD2L2 in maintaining glioblastoma stemness and promoting malignant behaviors through the regulation of c-MYC, suggesting its potential as a therapeutic target." (PMID 38017538, 2023). "The MAD2L2 exhibited high expression in glioblastoma samples and showed significant correlation with patient prognosis." (PMID 38017538, 2023). "The decreased tumor growth, accompanied by reduced Ki-67 expression, further supports the importance of MAD2L2 in promoting glioblastoma progression." (PMID 38017538, 2023). "To validate the biological function of MAD2L2 in glioblastoma progression in vivo, we injected MAD2L2-silenced U87 cells and corresponding control cells into the right axillary region of nude mice." (PMID 38017538, 2023). "In summary, our findings highlight the role of MAD2L2 in influencing glioblastoma stem cells maintenance through the regulation of c-MYC, thereby impacting malignant behaviors." (PMID 38017538, 2023). "In vitro and in vivo experiments confirmed that silencing of MAD2L2 led to decreased proliferation, invasion, and migration capabilities of glioblastoma cells, while decreasing stemness characteristics of glioblastoma stem cells." (PMID 38017538, 2023). "In our research, to further elucidate how MAD2L2 influences the proliferation and stemness of glioblastoma, we performed differential analysis and GSEA on GBM samples from three cohorts: TCGA-GBM, CGGA325, and CGGA693." (PMID 38017538, 2023). "Using bioinformatics methods, we discovered a positive correlation between MAD2L2 and E2F-1 expression in multiple publicly available glioblastoma datasets." (PMID 38017538, 2023). "Using UALCAN, we analyzed the expression of MAD2L2 in pan-cancer, including glioblastoma (GBM), and found that the transcription levels of MAD2L2 were significantly elevated in almost all cancer tissues compared to normal or adjacent tissues." (PMID 38017538, 2023).
ovarian tumor (1 paper, 2024). "IHC slides displayed moderate expression of MAD2L2 in ovarian tumor samples from three female patients aged 33, 35, and 65 years." (PMID 38167649, 2024). "Our study identifies MAD2L2 as a novel regulator in ovarian tumor progression and offers new insights for treating OVCA." (PMID 38167649, 2024).
rectal tumors (1 paper, 2019). "In the in vivo experiments, BTF3-siRNA inhibited the growth of rectal tumors, and in the microarray, we confirmed that BTF3 regulated the cell cycle related gene (MAD2L2, MCM3, and PLK1)." (PMID 31263147, 2019).
serous ovarian cancer (1 paper, 2024).
cancer (29 papers, 2015 to 2025). A tumor composed of atypical neoplastic, often pleomorphic cells that invade other tissues. "Similar to AURKB, MAD2L2 is dysregulated in different cancer cell lines and tumor tissues; MAD2L2 overexpression is associated with poor prognosis in various cancer types." (PMID 38515112, 2024). "Abolishing this gap filling role with an inhibitor that disrupts the interaction between REV1 and MAD2L2/REV3L is toxic to these HR-deficient cancer cells, including to PARP inhibitor-resistant BRCA1 mutant cells." (PMID 36075897, 2022). "However, somatic loss-of-function mutations in SAC, including that in MAD2L2, are rare and found in only a small fraction of cancers." (PMID 36012568, 2022). "Moreover, MAD2L2 is closely associated with cancer cell survival and may have implications as a potential pro-oncogene." (PMID 38017538, 2023). "Only 6 CDGs appeared under cell cycle and those were ANAPC13, ANAPC5, MAD2L2, GADD45G, CCND2, and surprisingly MYC — a gene often implicated as a cancer driver." (PMID 39774001, 2025). "We initially applied the gene expression profiling interactive analysis 2 (GEPIA2) to determine the expression of MAD2L2 in pan-cancer sample data between tumor samples and paired normal tissue samples taken from the same patient." (PMID 38167649, 2024). "Both AURKB and MAD2L2 are overexpressed in various human cancers and have synergistic oncogenic effects; therefore, they are regarded as emerging therapeutic targets for cancer." (PMID 38515112, 2024). "It has shown that MAD2L2 was involved in cell cycle regulation, DNA mismatch repair process, and cancer progression." (PMID 38167649, 2024). "MAD2L2 is implicated in response to DNA damage, potentially acting downstream of RIF1, contributing to genomic instability, a critical factor in cancer initiation." (PMID 38167649, 2024). "We found that the MAD2L2 expression in tumor tissues was significantly higher than the paired normal tissues in pan-cancer samples (P value < 0.05)." (PMID 38167649, 2024). "For example, MAD2L2 and LRRC61 are risk factors in most cancers, while PFKFB3, ESAM, SYNM, and LRFN5 act as protective factors in most cancers." (PMID 38124743, 2023). "We conducted an analysis of MAD2L2 expression in pan-cancer, including GBM, using the University of Alabama at Birmingham Cancer data analysis Portal (UALCAN)." (PMID 38017538, 2023). "The results revealed that the transcript levels of MAD2L2 were significantly elevated in almost all cancer tissues compared to normal or paraneoplastic tissues." (PMID 38017538, 2023). "REV7, REV1, and MAD2L2 interact with POLζ, and REV3L has been reported to cause drug resistance in several types of cancers." (PMID 29435169, 2018). "miR-890 sensitizes cancer cells to IR through multiple gene targets, including MAD2L2, supporting the concept that a single miRNA can simultaneously regulate multiple genes within a single pathway." (PMID 25845598, 2015). "Several studies have reported the coactivity of AURKB and MAD2L2 in cancer cells." (PMID 38515112, 2024). "However, there is a lack of mechanistic studies revealing the potential interactions and biofunctions between AURKB and MAD2L2 in cancer biology in BC cells." (PMID 38515112, 2024). "Furthermore, pan-cancer analysis revealed a significant positive correlation between MAD2L2 and E2F-1 expression across multiple cancer types." (PMID 38017538, 2023). "Recent studies showed that genetic inhibition of TLS through RNA-mediated depletion of Rev1, Rev3 or MAD2L2 indeed sensitizes a variety of cancer cells to DNA-damaging chemotherapeutics and suppresses the emergence of new tumor chemoresistance both in cancer cell lines and animal models." (PMID 35163901, 2022). "Moreover, MAD2L2 overexpression was found in several cancer types and is correlated with poor prognosis." (PMID 35163901, 2022). "Moreover, similar to AURKB, MAD2L2 was highly expressed in pan-cancer." (PMID 38515112, 2024).
cancer (continued). "This function of MAD2L2/REV3L is important because it prevents genomic instability arising from DNA replication stress, known to drive cancer development and progression." (PMID 36075897, 2022). "Of these, seven genes (BRIP1, ERCC4, FANCD2, FANCG, FANCI, MAD2L2, PPP2R2A) were previously related to the platinum sensitivity/resistance of different types of cancer cells, with NPEPPS being reported for the first time as a platinum drug sensitivity regulator." (PMID 35209078, 2022). "This role of MAD2L2/REV3L could be of particular importance in cancer biology, given that nucleotide exhaustion is a common feature shared by many cellular models of oncogene overexpression and that nucleotide synthesis inhibitors are widely used in cancer therapy." (PMID 36075897, 2022).
tumor (24 papers, 2016 to 2025). "Additionally, we discovered that tumor-associated transcription factors E2F-1 regulate MAD2L2 expression by directly binding to its promoter region." (PMID 38017538, 2023). "Moreover, higher expression of MAD2L2 was associated with lower tumor volume, earlier TNM stage, less invasion, and a smaller chance of distant metastasis in CRC patients, which suggested that MAD2L2 was a suppressor of CRC growth and metastasis." (PMID 29360267, 2018). "Loss of MAD2L2 can lead to genomic damage as a result of stalled replication forks and increased proliferation and migration, and thus has been posited to be a tumor suppressor though it may have an oncogenic role in some contexts." (PMID 40188944, 2025). "To further explore the function of AURKB and MAD2L2 in vivo, we established a T24 xenograft tumor model in nude mice." (PMID 38515112, 2024). "After finding that MAD2L2 was highly expressed in multi-tumor tissue, the clinical characteristics in OVCA patients were further evaluated." (PMID 38167649, 2024). "The subcutaneous injection of MAD2L2-silenced U87 cells demonstrated a decreased tumor growth rate compared to the control cells." (PMID 38017538, 2023). "To improve the predictive power of MAD2L2 in prognosis, we constructed a nomogram based on five factors: MAD2L2 expression, IDH mutation status, 1p19q codeletion status, tumor grades, and age." (PMID 38017538, 2023). "Further strengthening the anti‐tumour activity of pyridostatin against PARPi‐resistant tumours is its inhibitory effect against BRCA1‐deleted PDTXs, which carry inactivating mutations in the REV7 (MAD2L2) gene." (PMID 35107878, 2022). "In contrast, VHIO179, a tumour carrying BRCA1 germline truncation and previously shown to be resistant to treatment with PARPi due to an inactivating mutation in the MAD2L2 (REV7) gene, was hypersensitive to pyridostatin." (PMID 35107878, 2022). "The observation that SHLD2 or MAD2L2 siRNAs caused sensitivity to ART558 in a BRCA1 mutant cell line raised the possibility that a Polθ inhibitor could be used to target PARP inhibitor resistance caused by Shieldin complex defects when these occur in BRCA1 mutant tumour cells." (PMID 34140467, 2021). "In contrast with MAD2L2, expression of REV3L (encoding the catalytic subunit of Pol ξ) was significantly reduced in all three tumor types." (PMID 34663880, 2021). "Of the TLS factors profiled, only RAD18 and MAD2L2 (REV7) were overexpressed in all three tumor types." (PMID 34663880, 2021). "These in vivo results were consistent with our in vitro observations and confirmed the tumor suppressor role of MAD2L2 in CRC." (PMID 29360267, 2018). "Therefore, we employed the cBioPortal to detect the alternation types and frequency of MAD2L2 DNA in OVCA tumor samples based on the TCGA OVCA database." (PMID 38167649, 2024). "Additionally, similar tumor-promoting effects of MAD2L2 have been observed in ovarian and colon cancers." (PMID 38017538, 2023). "Importantly, VHIO179, a tumour carrying BRCA1 germline truncation, is resistant to treatment with PARP inhibitors due to a MAD2L2 (REV7) inactivating mutation." (PMID 31273933, 2019). "We have discovered a novel role of MAD2L2 in the regulation of NCOA3 degradation and proposed that MAD2L2 serves as a tumor suppressor in CRC." (PMID 29360267, 2018). "Collectively, these cellular experiments supported the inhibitory role of MAD2L2 in CRC development and suggested that MAD2L2 functioned as a tumor suppressor in CRC through the down‐regulation of NCOA3." (PMID 29360267, 2018). "Our study has discovered a novel role of MAD2L2 in regulating the degradation of NCOA3 and suggested that MAD2L2 functions as a tumor suppressor in CRC." (PMID 29360267, 2018).
tumor (continued). "Strikingly, the transcriptional regulator SPDEF was recently shown to act as a tumor metastasis suppressor in vivo and the multifactorial adaptor protein MAD2L2 (also known as MAD2B) was proposed to be involved in the TCF4-mediated epithelial-mesenchymal transdifferentiation." (PMID 26967245, 2016). "Besides, the Western blot results were consistent with the prediction data, which meant that in the MAD2L2 over-expressed OVCA cells, mTOR might upregulate SLC7A11 to restrain ferroptosis and promote tumor growth in OVCA cells." (PMID 38167649, 2024).
infection (2 papers, 2014 to 2021). The state of being infected such as from the introduction of a foreign agent such as serum, vaccine, antigenic substance or organism. "Further future research is also warranted to address whether the translocated EspF into the cells following infection interacts with MAD2L2 and its co-localization, combined with exploring the possible involvement of this interaction on cell cycle and/or APC/C parameters." (PMID 34575120, 2021).
MAD2L2 also shares sentences with these, for which no sentence is quoted: nasopharyngeal carcinoma (4 papers); esophageal SCC (3); diabetes (2); diabetic encephalopathy (2); diabetic nephropathy (2); diffuse large B-cell lymphoma (2); hyperglycaemia (2); lymphoma (2); prostate carcinoma (2); skin cancer (2); small cell lung carcinoma (2); teratoma (2); testicular cancer (2); testicular germ cell tumor (2); alopecia (1); Anxiety (1); autosomal recessive disease (1); basal cell carcinoma (1); bone marrow failure (1); breast tumors (1); cervical tumors (1); clear cell carcinoma (1); colorectal tumors (1); crescentic glomerulonephritis (1); embryonal carcinoma (1); fibrosarcoma (1); genetic disorder (1); invasive carcinoma (1); meningioma (1); metastatic melanoma (1).
A further 5 diseases each share a sentence with MAD2L2 in 1 paper.